MSLN (mesothelin)
Diseases named in the same sentence as MSLN in open-access papers (continued):
Sharing a sentence is not in itself a finding about the gene and the disease.
endometrial cancer (6 papers, 2018 to 2025). Primary or metastatic malignant neoplasm involving the endometrium (mucous membrane that lines the endometrial cavity). "This study aimed to investigate the association between clinicopathologic factors, mesothelin, and cancer antigen (CA) 125 in endometrial carcinoma." (PMID 33832498, 2021). "Mesothelin expression and co-expression might be associated with tumor aggressiveness and poor prognosis in patients with endometrial carcinoma." (PMID 33832498, 2021). "Herein, this study aimed to evaluate the correlation between the clinicopathological factors and either the expression of mesothelin or CA125 or co-expression of these biomarkers in endometrial carcinoma." (PMID 33832498, 2021). "Therefore, mesothelin may be a potential candidate for a new target therapy in endometrial carcinomas." (PMID 33832498, 2021). "In our study, only mesothelin expression and co-expression of mesothelin and CA125 were worse prognostic factors in several histological subtypes of endometrial carcinoma." (PMID 33832498, 2021). "Evaluating for mesothelin expression and co-expression of mesothelin and CA125 might be useful for the detection of aggressive subtypes of endometrial carcinomas." (PMID 33832498, 2021).
glioma (6 papers, 2017 to 2025). A benign or malignant brain and spinal cord tumor that arises from glial cells (astrocytes, oligodendrocytes, ependymal cells). "In this study, we describe for the first time the tissue expression and immunological recognition pattern of mesothelin in patients with gliomas." (PMID 29113296, 2017). "Clinical phase I trials are now warranted in order to develop cellular therapies for human CNS cancers using mesothelin as a target." (PMID 29113296, 2017). "H1299M (Mesothelin positive), LAN-1 (GD2 positive, mesothelin and EGFRvIII negative), K562 (GD2 negative), Glioma (EGFRvIII positive)." (PMID 31462392, 2019).
liver cancer (6 papers, 2021 to 2025). An epithelial or non-epithelial malignant neoplasm that arises from the liver. "Additional relevant biomarkers such as Mesothelin, Endoglin, AFP, and CEA contribute to classification, with color-coded SHAP values showing their differential impact between Ovarian and Liver cancer." (PMID 40217526, 2025).
melanoma (6 papers, 2016 to 2021). A malignant, usually aggressive tumor composed of atypical, neoplastic melanocytes. "Initial cancer vaccines predominantly targeted proteins expressed at higher levels in tumors compared with normal tissue, so-called tumor-associated antigens (TAA), such as gp100 in melanoma or mesothelin in pancreatic cancer." (PMID 35611186, 2021). "The association between anti-programmed cell death 1 (PD-1) therapy and activation of CD8 T cells specific for mutated antigens in melanoma may warrantstudies with mutated mesothelin-specific responses in patients with GBM undergoing immune checkpoint blockade therapy." (PMID 29113296, 2017).
meningioma (6 papers, 2017 to 2025). A generally slow growing tumor attached to the dura mater. "Mucin-16 (cancer antigen 125), a protein that is found in metastatic adenocarcinoma, has a high affinity for mesothelin, which has an increased expression in meningiomas." (PMID 39099765, 2024). "Carcinoma transmembrane mucins such as MUC16 have high affinity for mesothelin expressed in the leptomeninges and meningiomas." (PMID 36497364, 2022). "In addition, the leptomeninges and meningiomas express mesothelin that acts as an anchoring protein coupling with mucin-16." (PMID 36497364, 2022). "Because a number of adenocarcinomas express MUC16, and adenocarcinomas represent one of the most common carcinomas metastasizing to the leptomeninges, it is conceivable that an interaction with meningioma mesothelin and mucins facilitates anchoring by adenocarcinoma metastasis to meningiomas." (PMID 36497364, 2022). "Metastases may reflect expression of select groups of adhesion molecules on metastatic tumor cells and binding proteins such as mesothelin in the leptomeninges and meningiomas." (PMID 36497364, 2022). "The closest link between mesothelin and neuropathology in humans has been the observation that mesothelin is expressed in meningeal arachnoidal cells that may drive malignant transformation in meningioma." (PMID 29113296, 2017). "The expression of mesothelin in meningioma lead to the question whether the antigen is also expressed in malignant brain tumours, particularly GBM." (PMID 29113296, 2017). "Consequently, metastatic tumor cell mucin and mesothelin may also facilitate the anchoring of metastases to meningiomas." (PMID 36497364, 2022). "In fact, the cross-talk between mesothelin, a glycoprotein expressed on the cell membrane, and mucin-16 is thought to play a role in invasion and metastasis in TTM, in which adenocarcinoma, as the donor, metastasizes into meningioma, the recipient." (PMID 35001202, 2022).
colorectal adenocarcinoma (5 papers, 2014 to 2023). The most common type of colorectal carcinoma. "Recent studies revealed that ERC/mesothelin is expressed in about 50–60% of colorectal adenocarcinoma but not in normal colon epithelium." (PMID 35565327, 2022).
liver fibrosis (5 papers, 2018 to 2025). "MSLN has been implicated in the pathogenesis of liver fibrosis." (PMID 41400642, 2025). "Notably, immunotherapy strategies targeting MSLN have been demonstrated to effectively alleviate liver fibrosis, suggesting that MSLN represents a promising therapeutic target for anti-fibrotic treatment." (PMID 41400642, 2025). "When the composition of myofibroblasts was analyzed in livers of patients with liver fibrosis, the expression of MSLN and THY-1 was upregulated in livers of PSC patients, patients with biliary atresia, and biliary cirrhosis (but not in livers of patients with HCV liver fibrosis)." (PMID 34966784, 2021). "In human livers of PSC patients, expression of MSLN and THY1 are upregulated, showing a correlation with the stage of liver fibrosis." (PMID 36358290, 2022).
metastatic tumors (5 papers, 2015 to 2022). "One patient showed low MSLN expression in the primary tumour and high MSLN expression in the metastatic tumour." (PMID 36434635, 2022). "Three patients with high MSLN expression in their primary tumours showed low MSLN expression in their metastatic tumours." (PMID 36434635, 2022). "Four of these patients (23.5%) showed a discordance in MSLN expression between primary and metastatic tumours." (PMID 36434635, 2022). "More recently, the University of Pennsylvania group presented their experience using autologous T- cells modified with a chimeric antigen receptor (CAR) that recognizes mesothelin in pancreatic cancer patients with refractory metastatic disease." (PMID 26981244, 2016). "More recently, GVAX was combined with a Listeria vaccine that expresses mesothelin in 90 patients with metastatic disease." (PMID 26981244, 2016). "Furthermore, the concordance rate of high MSLN expression in primary and metastatic tumours was over 75% in our study." (PMID 36434635, 2022). "Among them, 17 had paired metachronous metastatic tumours for which MSLN expression could be assessed." (PMID 36434635, 2022). "There was a significant correlation between MSLN expression in primary and metastatic tumours." (PMID 36434635, 2022). "Moreover, the prognostic value of MSLN expression, its expression profiles in rare and aggressive histological types, such as gastric-type adenocarcinoma (GAS) and neuroendocrine carcinoma (NEC), and differences in its expression levels between primary and metastatic tumours remain unclear." (PMID 36434635, 2022).
renal carcinoma (5 papers, 2018 to 2025). A carcinoma arising from the epithelium of the renal parenchyma or the renal pelvis. "Expressed in Renal Carcinoma (ERC)/mesothelin is a glycosylphosphatidylinositol-anchored cell surface protein that is expressed in normal human mesothelium." (PMID 35565327, 2022). "In adults, expressed in renal cancer (ERC)/mesothelin is exclusively expressed in the mesothelial cells lining the pleural, pericardial, and peritoneal cavities, yet its function under physiological conditions is unknown." (PMID 40362566, 2025). "The expression of Renal Carcinoma (ERC)/mesothelin is enhanced in a variety of cancers." (PMID 35565327, 2022). "Human mesothelin has been proposed to be a malignancy factor as it increased tumor cell proliferation and migration in vitro and tumor size in nude mice, and siRNA specific for mesothelin suppressed tumor growth in a rat renal carcinoma model." (PMID 29474384, 2018). "Expressed in renal cancer (ERC) was first identified in a renal cell carcinoma of an Eker rat and is the homolog of human mesothelin (MSLN) or megakaryocyte potentiating factor." (PMID 40362566, 2025). "Expressed in Renal Carcinoma (ERC) was first identified in a renal cell carcinoma of an Eker rat, and is the homolog of human mesothelin (MSLN) or megakaryocyte potentiating factor." (PMID 32677949, 2020).
renal cell carcinoma (5 papers, 2015 to 2025). "In addition, our technique revealed not yet reported predicted MSLN amplifications in 10% of renal cell cancers and 5% of thyroid cancers." (PMID 26172299, 2015).
brain tumors (4 papers, 2017 to 2025). "CAR-M therapies directed against HER2 and EGFRvIII improved survival in preclinical models and are anticipated to cross the blood–brain barrier, while IL-13Rα2 and mesothelin have been validated as potential targets for brain tumor eradication." (PMID 41417432, 2025). "CAR-Ms targeting tumor-specific antigens such as EGFRvIII, IL-13Rα2, and mesothelin have also demonstrated considerable potential for treating brain tumors." (PMID 41417432, 2025). "Of note, one additional target was identified that shows preclinical favorability for the tumor differentiation antigen mesothelin (MSLN) for its overexpression in select solid tumors, including brain tumors." (PMID 35844304, 2022). "We therefore concluded that the mesothelin-specific response of patients with grade IV brain tumors has potential to be enhanced with IL-2/IL-15/IL-21 conditioning." (PMID 29113296, 2017). "Nevertheless, patients with grade III brain tumors may still have a benefit, due to a significant improvement in their IFN-γ response to the mesothelin precursor molecule." (PMID 29113296, 2017). "In the reanalysis, we found that patients with grade IV brain tumour (GBM), constituting the majority of group of the study cohort, exhibited a significantly increased IFN-γ response to MPF and mesothelin precursor peptide pool if the PBMCS were conditioned with IL-2/IL-15/IL-21." (PMID 29113296, 2017).
breast tumor (4 papers, 2016 to 2023). "With the purpose to develop a targeted therapy for MSLN-positive breast and non-breast tumors, we tested our candidate oncolytic THV_SS1 in cancer cell lines of different origin." (PMID 33418877, 2021). "Mesothelin is identified as a biomarker for TNBC because it is overexpressed in TNBC while its expression is limited in the common luminal breast tumor subtype and normal tissues." (PMID 27514374, 2016). "Mesothelin is identified as a biomarker for TNBC because some authors have identified its overexpression in TNBC and limited expression in the common luminal breast tumor subtype and normal tissues." (PMID 27514374, 2016).
gynecological cancers (4 papers, 2023 to 2026). "Overall, MSLN constitutes a promising target for precision oncology in gynecological cancers, although further clinical studies are required to validate its diagnostic utility and optimize targeted therapeutic approaches." (PMID 42279275, 2026). "We also detected relevant surface biomarkers of these gynecological cancers, such as MSLN, MUC1, and CD276, in the PSOs and respective tumor tissues obtained from the same clinical samples." (PMID 38162496, 2023).
ovarian serous carcinoma (4 papers, 2017 to 2025). "The aim of this review is to discuss the role of mesothelin in serous ovarian carcinomas, focusing on diagnostic, prognostic, and therapeutic perspectives." (PMID 35565412, 2022). "Among the tumors analyzed, the highest frequencies of mesothelin-positivity were detected in ovarian serous carcinoma (90% in 5B2 and 94% in MN-1)." (PMID 28460459, 2017). "Among them, high frequencies of mesothelin-positivity were detected in ovarian serous carcinoma (90%, median value of positive cells 90% in 5B2 and 94%, median value of positive cells 100% in MN-1)." (PMID 28460459, 2017). "Almost all ovarian serous carcinomas showed high-levels of mesothelin expression with both 5B2 and MN-1 anti-mesothelin antibodies." (PMID 28460459, 2017). "We found that MSLN was highly expressed in ovarian clear cell carcinoma, high-grade serous ovarian carcinoma, low-grade serous ovarian carcinoma, mucinous ovarian carcinoma, mucinous-serous cystadenocarcinoma of the ovary; in contrast, its expression is low in normal tissues." (PMID 35692779, 2022).
sarcomatoid mesothelioma (4 papers, 2014 to 2025). A diffuse malignant mesothelioma arising from the pleura and less often the peritoneum. "Excluding the five sarcomatoid mesothelioma cases from the analysis revealed higher AUCs of 0.85 for mesothelin, 0.78 for miR-103a-3p, and 0.93 for the combination of mesothelin and miR-103a-3p." (PMID 25469901, 2014). "It is well known that mesothelin fails to detect sarcomatoid mesothelioma and this is also shown in this study." (PMID 25469901, 2014). "Anti-mesothelin mAbs react with epithelial but not sarcomatoid mesotheliomas." (PMID 27342200, 2016). "Notably, utilizing the recommended cut-off for mesothelin (1.5 nmol/l) resulted in 65% sensitivity and 85% specificity for all subjects and 71% sensitivity and 85% specificity for subjects without sarcomatoid mesothelioma." (PMID 25469901, 2014).
small cell lung carcinoma (4 papers, 2017 to 2023). Small cell lung cancer (SCLC) is a highly aggressive malignant neoplasm, accounting for 10-15% of lung cancer cases, characterized byrapid growth, and early metastasis. "Since mesothelin has not been described on small cell lung cancer (SCLC), these patients were not as relevant to our examination of TriKE function." (PMID 36911670, 2023).
clear cell renal cell carcinomas (3 papers, 2017 to 2025). "Urothelial carcinomas and clear cell renal cell carcinomas showed rare positivity for mesothelin with both antibodies (4–13%)." (PMID 28460459, 2017). "MSLN immunostaining was unrelated to overall survival in 227 bladder carcinomas (p = 0.3302; only pT ≥ 2), 593 invasive breast carcinomas of no special types (p = 0.0976), and 502 clear cell renal cell carcinomas (p = 0.3144)." (PMID 33917081, 2021).
endometrioid carcinoma (3 papers, 2021 to 2025). "In addition, target genes such as CD74, MSLN, NaPi2b and VEGF are more highly expressed in serous than in mucinous, clear and endometrioid carcinomas." (PMID 40046734, 2025). "Only a few patients had grade 1 endometrioid carcinoma and more had other types of carcinomas in the groups with positive mesothelin expression than in those with negative mesothelin expression (p = 0.027)." (PMID 33832498, 2021).
pleural tumors (3 papers, 2017 to 2024). "The mPBPK-PD model with a pleural tumor captured cellular kinetic profiles from a mouse pleural tumor model treated with anti-mesothelin CAR T cells through i.v. or intrapleural administration." (PMID 35869348, 2022).
synovial sarcoma (3 papers, 2015 to 2022). "We showed high percentages of predicted MSLN amplification in gynecological tumors, gastrointestinal tumors, NSCLC and synovial sarcomas." (PMID 26172299, 2015). "Predicted amplification of MSLN was most frequently found in gynecological tumors, gastrointestinal tumors, NSCLC (21% of N = 612) and in synovial sarcoma (30% of N = 34)." (PMID 26172299, 2015). "However, we need to keep in mind that there is a broad range of tumour types, such as gastric, colorectal, oesophageal carcinomas, and synovial sarcoma, which although not arising from the mesothelium, can express MSLN." (PMID 35565412, 2022).
uterine cancer (3 papers, 2021 to 2023). Primary or metastatic malignant neoplasm involving the uterine corpus and/or the cervix. "Furthermore, the in vivo proliferation of human uterine -cancer cells with mesothelin expression was inhibited by treatment with a mesothelin-targeting antibody-based drug." (PMID 33832498, 2021).
asbestosis (2 papers, 2017 to 2023). A lung disorder caused by inhalation of asbestos fibers. "Indeed, high levels of ATG5, miR-222 and mesothelin were associated with the presence of benign ARDs, such as asbestosis and/or pleural plaques." (PMID 37095543, 2023). "The small differences between plaques and asbestosis were statistically significant for calretinin (p = 0.0084) as well as mesothelin (p = 0.0048)." (PMID 28558669, 2017).
bladder cancer (2 papers, 2021 to 2024). "However, the absence of statistical associations between MSLN expression and tumor phenotype and/or prognosis in carcinomas of the bladder, breast, ovary, endometrium, kidney, lung, and stomach argues against a major prognostic role of MSLN expression levels." (PMID 33917081, 2021).
brain cancer (2 papers, 2017 to 2025). A primary or metastatic malignant neoplasm affecting the brain. "After we had confirmed that patients with brain cancer can mount a measurable cellular immune responses to the mesothelin precursor, we wanted to map which epitopes within the mesothelin protein would evoke the strongest IFN-γ response by T cells." (PMID 29113296, 2017).
breast invasive carcinoma (2 papers, 2021 to 2024).
cervical squamous cell carcinoma (2 papers, 2024). A squamous cell carcinoma arising from the cervical epithelium. "Conversely, it correlates with the downregulation of MSLN in cervical squamous cell carcinoma and endocervical adenocarcinoma (CESC)." (PMID 39186767, 2024).
cholestasis (2 papers, 2022 to 2024). Impairment of the bile flow caused by obstruction within the liver, or outside the liver in the bile duct system. "MUC16 is a ligand for MSLN, and MSLN requires MUC16 for intracellular signaling to activate the MSLN/MUC16/AKT pathway, regulating cholestasis-induced proliferation of activated portal fibroblasts/myofibroblasts, but not affecting Fibrotic properties of APFs." (PMID 38758220, 2024).
chronic pancreatitis (2 papers, 2012 to 2025). A chronic inflammatory process causing damage and fibrosis of the pancreatic parenchyma. "Mesothelin mRNA level in pure pancreatic juice by RT-PCR was found in 11 (52%) of 21 pancreatic carcinomas, 5 (45%) of 11 IPMNs, and 3 (14%) of 22 with chronic pancreatitis." (PMID 24278753, 2012). "Mesothelin expression was identified in pancreatic juice in about 45% of ductal carcinoma or IPMN, but 14% in chronic pancreatitis (by RT-PCR for mRNA)." (PMID 24278753, 2012).